CDK4 (cyclin dependent kinase 4)
Description:
Ser/Thr-kinase component of cyclin D-CDK4 (DC) complexes that phosphorylate and inhibit members of the retinoblastoma (RB) protein family including RB1 and regulate the cell-cycle during G(1)/S transition. Phosphorylation of RB1 allows dissociation of the transcription factor E2F from the RB/E2F complexes and the subsequent transcription of E2F target genes which are responsible for the progression through the G(1) phase. Hypophosphorylates RB1 in early G(1) phase. Cyclin D-CDK4 complexes are major integrators of various mitogenenic and antimitogenic signals. Also phosphorylates SMAD3 in a cell-cycle-dependent manner and represses its transcriptional activity. Component of the ternary complex, cyclin D/CDK4/CDKN1B, required for nuclear translocation and activity of the cyclin D-CDK4 complex.
Synonyms: PSK-J3; CMM3; MCPH31
Tractability: Small molecule: an approved drug acts on it; a structure with a bound ligand is known; a high-quality ligand is known; it has a high-quality binding pocket; it belongs to a druggable protein family. PROTAC: it is named in the literature on targeted protein degradation; ubiquitination databases record sites on it; its protein half-life has been measured; a small molecule that binds it is known.
Target class: CMGC protein kinase group; Protein Kinase; Enzyme; Kinase
Chemical probes: ABEMACICLIB (high quality), BSJ-03-123 (high quality), BSJ-03-204 (high quality), BSJ-04-132 (high quality), PALBOCICLIB (high quality), PD134503, PD134504, PD134505, PD134506, PD134507
Gene: Protein-coding gene on chromosome 12 (57,747,722 to 57,756,013, reverse strand). Ensembl gene ENSG00000135446.
Subcellular location: Cytoplasm; Nucleus; Nucleus membrane
Subcellular location (Human Protein Atlas): Cytosol; Nucleoplasm; Nuclear membrane; Nucleoli
Pathways (Reactome):
Disease: Defective binding of RB1 mutants to E2F1,(E2F2, E2F3); Evasion of Oncogene Induced Senescence Due to Defective p16INK4A binding to CDK4; Evasion of Oncogene Induced Senescence Due to Defective p16INK4A binding to CDK4 and CDK6; Evasion of Oxidative Stress Induced Senescence Due to Defective p16INK4A binding to CDK4; Evasion of Oxidative Stress Induced Senescence Due to Defective p16INK4A binding to CDK4 and CDK6
Cell Cycle: Cyclin D associated events in G1; Drug-mediated inhibition of CDK4/CDK6 activity; SCF(Skp2)-mediated degradation of p27/p21; Ubiquitin-dependent degradation of Cyclin D
Cellular responses to stimuli: Oncogene Induced Senescence; Oxidative Stress Induced Senescence; Senescence-Associated Secretory Phenotype (SASP)
Developmental Biology: Transcriptional regulation of granulopoiesis; Transcriptional regulation of white adipocyte differentiation
Chromatin organization: RMTs methylate histone arginines
Gene expression (Transcription): Transcriptional regulation by RUNX2
Immune System: SPOP-mediated proteasomal degradation of PD-L1(CD274)
Reproduction: Meiotic recombination
Signal Transduction: PTK6 Regulates Cell Cycle
Gene Ontology:
Molecular function: cyclin binding; cyclin-dependent protein serine/threonine kinase activity; protein binding; protein serine kinase activity; cyclin-dependent protein serine/threonine kinase regulator activity; ATP binding; kinase activity; protein kinase activity
Biological process: G1/S transition of mitotic cell cycle; positive regulation of cell population proliferation; positive regulation of fibroblast proliferation; positive regulation of G2/M transition of mitotic cell cycle; regulation of cell cycle; regulation of gene expression; response to xenobiotic stimulus; G2/M transition of mitotic cell cycle; regulation of transcription initiation by RNA polymerase II
Cellular component: chromatin; cyclin D1-CDK4 complex; cyclin D2-CDK4 complex; cyclin D3-CDK4 complex; cyclin-dependent protein kinase holoenzyme complex; cytoplasm; cytosol; nuclear membrane; nucleolus; nucleoplasm; nucleus; bicellular tight junction; transcription regulator complex
Genetic constraint (gnomAD): Loss-of-function variants: 13 observed, 33.88 expected, observed/expected ratio (o/e) 0.38, 90% interval 0.25 to 0.61. The upper end of that interval is the gene's LOEUF score, 0.61, which puts it in group 2 of 6, group 1 being the genes least tolerant of losing a copy. Missense variants: 274 observed, 397.07 expected, observed/expected ratio (o/e) 0.69, 90% interval 0.62 to 0.76. Synonymous variants: 156 observed, 153.86 expected, observed/expected ratio (o/e) 1.01, 90% interval 0.89 to 1.16.
Gene-disease validity (ClinGen):
ClinGen rates the evidence that CDK4 causes each of these diseases.
melanoma, cutaneous malignant, susceptibility to, 3 (autosomal dominant): Definitive.
Cancer hallmarks: cell replicative immortality (promotes)
Homologues: Orthologues: chimpanzee CDK4 (100% identical), macaque CDK4 (99% identical), guinea pig CDK4 (98% identical), pig CDK4 (98% identical), rabbit CDK4 (97% identical), mouse Cdk4 (95% identical), rat Cdk4 (87% identical), tropical clawed frog cdk4 (75% identical), zebrafish cdk4 (70% identical). Paralogues in human: CDK6 (70% identical), CDK3 (44% identical), CDK5 (44% identical), CDK2 (43% identical), CDK10 (42% identical), CDK1 (42% identical), CDK13 (41% identical), CDK18 (41% identical), CDK12 (40% identical), CDK17 (40% identical), CDK11A (40% identical), CDK11B (40% identical), and 14 more.
Diseases named in the same sentence as CDK4 in open-access papers:
CDK4 is named in the same sentence as 469 diseases in open-access papers, as found by Europe PMC text mining. Sharing a sentence is not in itself a finding about the gene and the disease. The quoted sentences say what the papers report.
breast cancer (1,827 papers, 2006 to 2026). A primary or metastatic malignant neoplasm involving the breast. "Given that CDK4/6 inhibitors are primarily employed in the luminal A/B (ER+) breast cancer subtype, METTL1 appears to be closely associated with this subtype." (PMID 41501031, 2026). "This non-apoptotic mechanism is particularly relevant for therapeutic strategies targeting cell cycle progression in cancer cells, where CDK4 overexpression has been linked to poor prognosis and increased cell proliferation in breast cancer." (PMID 40864776, 2025). "PTEN-deficient breast cancers have worse disease-free and overall survival rates and have been linked to reduced efficacy of CDK4/6 inhibitors and PI3K/AKT/mTOR pathway inhibitors." (PMID 40565165, 2025). "In summary, the combination of Inavolisib and CDK4/6 inhibitors provides a new treatment paradigm for PIK3CA-mutated breast cancer by synergistically blocking the PI3K signaling pathway and cell cycle progression." (PMID 41280894, 2025). "Here, we discuss the molecular mechanisms underlying cell cycle regulation and resistance to CDK4/6 inhibitors in breast cancer." (PMID 39930131, 2025). "A multicenter retrospective study involving 16 patients with stage IV breast cancer reported that VLD was associated with CDK4/6 inhibitor treatment (14 of 16 were treated with ribociclib, and two of 16 with palbociclib)." (PMID 40861456, 2025). "A caveat is that in breast cancer preclinical models, in contrast to our ccRCC models, pRB inactivation is sufficient to cause resistance to CDK4/6 inhibitors." (PMID 40178040, 2025). "To investigate the mechanisms underlying endocrine and CDK4/6 inhibitor resistance in early-stage ER+ breast cancer cells, we employ a hybrid computational and experimental strategy." (PMID 40341770, 2025). "RB1 knockout cells were used due to the prevalence of RB1 mutations in breast cancer conveying resistance to CDK4/6 inhibitors." (PMID 40650785, 2025). "Although CDK4/6 inhibitors have improved survival in patients with HR + /HER2- advanced breast cancer, they are also associated with some adverse events (AEs)." (PMID 41259313, 2025). "This study aims to evaluate the incidence and clinical characteristics of ILD associated with CDK4/6 inhibitors in breast cancer patients in Turkey." (PMID 40142360, 2025). "Genomic analysis of baseline HR+/HER− breast cancer biopsy samples revealed LOF mutations in the FAT1 gene as a significant predictor of early progression on CDK4/6 inhibitors." (PMID 39930131, 2025). "In PIK3CA-mutated HR+/HER2- breast cancer, targeted degradation and inhibition of mutant p110α with inavolisib combined with CDK4/6 inhibition offers a compelling strategy to block both oncogenic signaling and cell-cycle progression." (PMID 41280894, 2025). "The role of the CDK4 rs2069502 polymorphism in human prostate carcinogenesis has not been previously investigated, though it has been examined in breast cancer." (PMID 40304827, 2025). "Mechanistically, Simvastatin downregulates CDK4 expression, a pivotal regulator of G1/S transition whose overexpression is associated with poor prognosis in breast cancer." (PMID 40864776, 2025). "Accordingly, reparixin in association with CDK4/6is, is promising to counteract endocrine-refractory breast cancer progression and diffusion." (PMID 40244377, 2025). "Given that RB loss is a well-established mechanism of resistance to CDK4/6 inhibitors in breast cancer patients, we wished to verify these findings using independent breast cancer models." (PMID 40940326, 2025). "Abundant preclinical findings have revealed that CDK4/6 is essential for breast cancer cell for enduring the ability to cause tumors." (PMID 40035822, 2025). "In HR positive advanced breast cancer patients treated with first-line CDK4/6 inhibitors, lower BMI is associated with poorer prognosis." (PMID 41346024, 2025).
breast cancer (continued). "A total of 49,223 female breast cancer cases with reported adverse events associated with CDK4/6is were identified, including 4918 cases (10.0 %) for abemaciclib, 38,002 (77.2 %) for palbociclib, and 6303 (12.8 %) for ribociclib." (PMID 41496429, 2025). "Combined use of endocrine therapy and CDK4/6 inhibition is now standard-of-care for patients with ER+ breast cancer, including those with high-risk early-stage and advanced disease." (PMID 40826108, 2025). "Simvastatin induced G1 phase cell cycle arrest in MDA-MB-231 and ZR-75-1 breast cancer cells, which was associated with the downregulation of CDK4." (PMID 40864776, 2025). "This study shows that while common senolytic compounds are unable to eliminate CDK4/6i-treated malignant cells, CDK4/6i elicits lysosome alterations that render breast cancer cells susceptible to combined therapy." (PMID 39930269, 2025). "The current study supports concerns about the risk of OAEs when breast cancer patients use CDK4/6 inhibitors." (PMID 41282629, 2025). "In a separate study on HER2+ breast cancer, acquired resistance to CDK4/6 co-targeting therapy was associated with the presence of an immunosuppressive immature myeloid cell population resembling MDSCs." (PMID 40058234, 2025). "Clinical trials like MonarchE and NATALEE have established important criteria for defining high-risk early breast cancer and demonstrated the efficacy of adding CDK4/6i to standard endocrine therapy in these populations." (PMID 40377782, 2025). "JNK activation has been shown to drive CDK4/6 inhibitor resistance and is associated with poor prognosis in luminal B type breast cancers." (PMID 40826108, 2025). "The oral, selective, and potent small molecule cyclin-dependent kinases (CDK) 4/6 inhibitor (CDK4/6i) abemaciclib has demonstrated efficacy in advanced breast cancer and high-risk early breast cancer." (PMID 40144206, 2025). "Noteworthy, HMGB1 elevated expression in breast cancer is associated with a poorer response, though it also predicts greater benefit from CDK4/6 inhibitors, establishing HMGB1 not only as a resistance target but also as a predictive biomarker." (PMID 41465435, 2025). "Overexpression of the CCND1 gene, which encodes cyclin D1 (the primary partner of CDK4/6), has been commonly observed in breast cancers resistant to CDK4/6is." (PMID 40244377, 2025). "Palbociclib, in contrast, acts further downstream and was included in this analysis given its role in the inavolisib regimen as well as prior reports linking CDK4/6 inhibitors to an increased risk of stomatitis in breast cancer patients." (PMID 41155694, 2025). "In Rb1-deficient tumors—including CDK4/6i-resistant breast cancer—upregulation of mitosis-associated E2F target genes provides a therapeutic opportunity for AURKA inhibitors to trigger replication stress via synthetic lethality, leading to tumor cell death." (PMID 40949156, 2025). "One mechanism by which breast cancer cells develop resistance to CDK4/6 inhibitors involves the degradation or mutation of the retinoblastoma (RB) protein." (PMID 40303296, 2025). "This review synthesizes preclinical and clinical evidence on the mechanistic optimization of inavolisib combined with CDK4/6 inhibitors for PIK3CA-mutated breast cancer." (PMID 41280894, 2025). "In breast cancer, the enhanced activity of pro-aggressive transcription factors such as NF-κB, AP-1, and E2F has been associated with resistance to CDK4/6is." (PMID 40244377, 2025). "Our study, the first of its kind conducted in Turkey, aims to determine the incidence of CDK4/6 inhibitor-associated ILD in breast cancer patients and to characterize the clinical features of the affected patients." (PMID 40142360, 2025). "In the current study, we identified NSRP1 as a downregulated RBP in CDK4/6i resistant breast cancer whose high expression was associated with good prognosis of patients with ER+ breast cancer." (PMID 39667501, 2025).
breast cancer (continued). "In cluster 2, which is enriched for ER+ and/or HER2+ breast cancer and Ewing sarcoma, many cell lines that were sensitive to CDK4 loss were less affected by CDK2 depletion, suggesting a reciprocal relationship in the requirements of these kinases." (PMID 39924553, 2025). "INAVO-121 will compare inavolisib plus fulvestrant with alpelisib plus fulvestrant in a population with PIK3CA-mutated, ER+/HER2− advanced, or relapsed breast cancer progressing after ET plus CDK4/6is (NCT05646862)." (PMID 40244377, 2025). "Approximately 30% of patients with HR+/HER2− breast cancer who develop resistance to CDK4/6 inhibitors acquire new genetic mutations." (PMID 39930131, 2025). "In one study, the effectiveness of CDK4/6is in relapsed breast cancer with ESR1 mutations (ESR1m) was assessed using circulating tumor DNA (ctDNA) analysis." (PMID 40244377, 2025). "CCNE1, a member of the cyclin family, was reportedly involved in cell cycle progression in breast cancer patients, since higher expression was associated with clinical resistance to a CDK4/6 inhibitor." (PMID 40022573, 2025). "Breast cancer cells harboring Rb LOF mutations are unresponsive to CDK4/6 inhibitors, but this primary resistance can be reversed by reintroducing wild-type Rb54." (PMID 39930131, 2025). "Preclinical data have implicated cyclin D1/CDK4 in resistance to therapy in HER2+ breast cancer and the potential of CDK4/6i to overcome this resistance, providing rationale for the investigation of abemaciclib in combination with HER2-targeted therapy." (PMID 40144206, 2025). "Herein, this study analyzed adverse reactions in breast cancer patients receiving a CDK4/6 inhibitor abemaciclib, with a focus on identifying risk factors for diarrhea and neutropenia through regression analysis." (PMID 40620712, 2025). "This study retrospectively analysed clinical data from patients with metastatic HR-positive breast cancer treated with CDK4/6 inhibitors, revealing that a high BMI was linked to poorer overall survival outcomes following CDK4/6 inhibitor therapy." (PMID 41346024, 2025). "A recent work reports that RANK overexpression in luminal breast cancer is associated with CDK4/6 inhibitor and decreased chronic IFN-γ response." (PMID 39827158, 2025). "Dysregulation of the cell cycle machinery, particularly the overactivation of cyclin-dependent kinases 4 and 6 (CDK4/6), is a hallmark of breast cancer pathogenesis." (PMID 39930131, 2025). "Resistance to CDK4/6 inhibitors in breast cancer is increasingly linked to hormonal pathway rewiring and transcriptional reprogramming, exemplified by hormone receptor (HR) loss and AP-1 overexpression." (PMID 40421216, 2025). "Dysregulation of this pathway, particularly through CDK4 overexpression, contributes to unchecked cellular proliferation and is frequently associated with poor prognosis in various cancers, including breast carcinoma." (PMID 40864776, 2025). "CDK4/6 inhibitors have improved outcomes for patients with ER+ breast cancer, however, those with loss of RB1 function often fail to respond." (PMID 38480701, 2024). "In conclusion, PR-negative and first-line POD24 occurrence were risk factors of advanced ER-high HER2-negative breast cancer patients receiving CDK4/6 inhibitor combined with endocrine as first-line therapy." (PMID 39020297, 2024). "Several trials have investigated the efficacy and safety of CDK4/6 inhibitors and they have been approved for the treatment of advanced ER+ and early high-risk breast cancer." (PMID 38791941, 2024). "Resistance to CDK4/6i and ET for HR+ breast cancer is found to be associated with alterations in the PI3K/AKT/mTOR pathway." (PMID 39409880, 2024). "CCND1 activation of CDK4/6 kinases and its upregulation is associated with ER positivity, poor outcomes, and resistance to endocrine therapy in ER+ breast cancer patients." (PMID 38275906, 2024).